MOG (myelin oligodendrocyte glycoprotein)
Diseases named in the same sentence as MOG in open-access papers (continued):
Sharing a sentence is not in itself a finding about the gene and the disease.
acute disseminated encephalomyelitis (203 papers, 2010 to 2026). Acute disseminated encephalomyelitis (ADEM) is a demyelinating disorder of the central nervous system. "MOG antibodies have already been implicated in demyelinated diseases, such as ON and acute disseminated encephalomyelitis (ADEM), and have recently been shown to be potential markers for differentiating atypical ON from other ON phenotypes." (PMID 41017978, 2025). "Four children were diagnosed with myelin oligodendrocyte glycoprotein (MOG) antibody‐associated acute disseminated encephalomyelitis, a condition known to cause CSF eosinophilia in about one‐third of patients." (PMID 39821425, 2025). "The typical phenotypes of myelin oligodendrocyte glycoprotein antibody-associated disease (MOGAD) in children include acute disseminated encephalomyelitis (ADEM), optic neuritis (ON), neuromyelitis optica spectrum disorder, and transverse myelitis." (PMID 40078175, 2025). "Antibodies to the glial protein MOG can be associated with acute disseminated encephalomyelitis (more frequent in the pediatric population) and cerebral cortical encephalitis (more frequent in adults), and, as such, have been included into the spectrum of AE." (PMID 38507081, 2024). "Acute disseminated encephalomyelitis (ADEM) is the most common clinical manifestation associated with anti-MOG antibodies." (PMID 37090723, 2023). "This case report demonstrates the management of an adolescent with myelin-oligodendrocyte glycoprotein (MOG) antibody-associated fulminant acute disseminated encephalomyelitis (ADEM)." (PMID 37465442, 2022). "Myelin oligodendrocyte glycoprotein (MOG) antibody-associated disorder (MOGAD) is a newly identified autoimmune demyelinating disorder that is often associated with acute disseminated encephalomyelitis and usually occurs postinfection or postvaccination." (PMID 35299613, 2022). "Recently, a robust association of anti-MOG IgG has been found with optic neuritis, myelitis and brainstem encephalitis, as well as with acute disseminated encephalomyelitis (ADEM)-like presentations." (PMID 35140707, 2021). "Acute disseminated encephalomyelitis (ADEM) is the clinical form that is most frequently associated with anti-MOG (40%), but these antibodies are also detected in NMOsd." (PMID 31752329, 2019). "Autoantibodies against MOG are implicated in pediatric MS and acute disseminated encephalomyelitis (ADEM) as well as in a subset of water channel aquaporin-4 (AQP4)-IgG seronegative neuromyelitis optica spectrum disorder (NMOSD)." (PMID 28646890, 2017). "Therefore, PRES-SCI must be differentiated from inflammatory diseases that can cause spinal cord lesions, such as NMOSD, anti-MOG antibody-associated disease, acute disseminated encephalomyelitis, neuro-sarcoidosis, and myelitis due to collagen disease." (PMID 40395249, 2025). "In other words, even outside the demyelinating spectrum syndromes such as ADEM (acute disseminated encephalomyelitis), MOG antibodies are not only associated with autoimmune encephalitis in children, but also they are the most frequent biomarkers in this scenario." (PMID 35976312, 2022). "MOG-Abs have been strongly associated with several demyelinated disorders such as acute disseminated encephalomyelitis (ADEM), pediatric MS, transverse myelitis, optic neuritis (ON), and neuromyelitis optical spectrum disorders (NMOSD), but are rarely detected in patients with MS." (PMID 34681255, 2021). "ON is the prominent aspect of the less frequent NMO as well as myelin oligodendrocyte glycoprotein (MOG) antibody‐associated disease, while it can develop in combination with Lyme disease, vasculitis, acute disseminated encephalomyelitis, syphilis, and sarcoidosis." (PMID 34520634, 2021). "Anti-MOG antibody associated demyelination (MOGAD) frequently presents as Acute Disseminated Encephalomyelitis (ADEM) in children and opticospinal involvement in young adults." (PMID 39728905, 2024).
acute disseminated encephalomyelitis (continued). "Antibodies against conformational MOG epitopes detected by cell-based assay (CBA) were later causally implicated in acute disseminated encephalomyelitis (ADEM) and NMOSD." (PMID 34097296, 2022). "The phenotype of MOG-IgG-associated encephalitis is similar to acute disseminated encephalomyelitis (ADEM) presenting with seizures, abnormal behavioral and psychological symptoms, and cognitive impairment." (PMID 36530610, 2022). "Both patients had a clinical phenotype of acute disseminated encephalomyelitis (ADEM) and fulfilled MOGAD (MOG ab‐associated disease) criteria, according to a recent international panel." (PMID 40318023, 2025). "The current literature reports MOG-associated meningoencephalitis and acute disseminated encephalomyelitis (ADEM) after M. pneumoniae infections, but MOG-IgG-associated encephalitis induced by M. pneumoniae infections has not been reported." (PMID 39334394, 2024). "CNS IDDs include multiple sclerosis (MS), neuromyelitis optica spectrum disorders (NMOSDs), myelin oligodendrocyte glycoprotein antibody-associated disease (MOGAD), acute disseminated encephalomyelitis (ADEM), optic neuritis (ON), and transverse myelitis (TM)." (PMID 38534984, 2024). "Since the advent of highly specific cell-based assays, MOG antibodies have frequently been detected in patients with optic neuritis, neuromyelitis optica, myelitis, acute disseminated encephalomyelitis (ADEM), brainstem encephalitis, and cortical encephalitis." (PMID 36688157, 2022). "Accordingly, acute disseminated encephalomyelitis (ADEM) is a frequent manifestation of MOG-EM, especially in children." (PMID 35737110, 2022). "Using the CBA, MOG-IgG was also detected in acute disseminated encephalomyelitis (ADEM), encephalitis, optic neuritis (ON), and myelitis." (PMID 35898513, 2022). "Recent advances in detection methods using cell-based assays revealed that MOG-Ab was present in the peripheral blood of various inflammatory CNS diseases, especially pediatric diseases including acute disseminated encephalomyelitis." (PMID 34991631, 2022). "Acute disseminated encephalomyelitis (ADEM) is generally preceded by an infection or rarely by vaccination and it is associated with an immunoreactive process against MOG antigens." (PMID 36289819, 2022). "Recently, findings showed that the antibodies to MOG in certain NMO IgG‐seronegative patients with neuroimaging and clinical symptoms of NMO or NMOSD present a variant of the opticospinal MS or acute disseminated encephalomyelitis." (PMID 34520634, 2021). "The association between anti-MOG antibody and inflammatory demyelinating diseases of the CNS, such as NMO, and acute disseminated encephalomyelitis (ADEM), has been reported." (PMID 33847609, 2021). "One of the two participants with MOG antibodies reported a 1-week history of constant nausea associated with acute disseminated encephalomyelitis (ADEM)-like lesions in the bilateral cerebral hemispheres and poorly demarcated dorsal midbrain and pontine lesions around the fourth ventricle." (PMID 32581992, 2020). "Clinical presentations included a combination of optic neuritis, transverse myelitis, and acute disseminated encephalomyelitis for 81 of 84 anti-MOG antibody–positive children (96%)." (PMID 31545352, 2020). "The MOG antibody (MOG-Ab) has been identified in pediatric patients with acquired demyelinating syndrome, particularly the acute disseminated encephalomyelitis (ADEM)." (PMID 31440204, 2019). "Specific antibodies against MOG are detectable in pediatric patients with acute disseminated encephalomyelitis (ADEM)." (PMID 30405519, 2018). "Anti-MOG antibodies were defined in patients with acute disseminated encephalomyelitis (ADEM), uni- or bilateral optic neuritis, transverse myelitis, longitudinally extensive transverse myelitis, and neuromyelitis optica." (PMID 30364136, 2018).
acute disseminated encephalomyelitis (continued). "Anti-MOG antibody is predominantly detected in pediatric acute disseminated encephalomyelitis (ADEM), recurrent optic neuritis, and aquaporin-4 antibody-seronegative neuromyelitis optica spectrum disorder (NMOSD)." (PMID 28420330, 2017). "On the other hand, MOG is produced by the oligodendrocytes and is recognized as the target autoantigen candidate in acute disseminated encephalomyelitis (ADEM) and a selective subgroup of adult type II MS (antibody-mediated demyelination)." (PMID 28203460, 2017). "MOG-IgG have also been reported in children with acute disseminated encephalomyelitis, a condition with suspected post-infectious or post-vaccinal etiology." (PMID 27802825, 2016). "Autoantibodies against MOG are reportedly found in patients with a spectrum of inflammatory demyelinating diseases of the CNS, including acute disseminated encephalomyelitis, multiple sclerosis, transverse myelitis, and neuromyelitis optica (NMO)." (PMID 25434485, 2014). "Antibody responses against MOG are mainly found in pediatric demyelinating diseases like acute disseminated encephalomyelitis and pediatric MS." (PMID 23035757, 2012). "High-titer IgG autoantibodies to conformational epitopes of MOG (MOG-IgG) were detected in a subgroup of pediatric patients with acute disseminated encephalomyelitis (ADEM) and MS, but rarely in adult-onset MS." (PMID 22204662, 2011). "Although current data are limited, there is indication that local complement activated by self-antibodies to the myelin oligodendrocyte glycoprotein (MOG) may also contribute to acute disseminating encephalomyelitis (ADEM) through cell destruction." (PMID 39022733, 2024). "In addition, cases of anti-MOG antibody-positive acute disseminated encephalomyelitis, a CNS demyelinating disorder, have been reported following infectious mononucleosis due to primary EBV infection." (PMID 38138980, 2023). "Antibodies against MOG have been associated with a wide variety of clinical phenotypes, including acquired demyelinating syndromes such as optic neuritis, myelitis, acute disseminated encephalomyelitis (ADEM), neuromyelitis optical spectrum disorder (NMOSD), encephalitis, and aseptic meningitis." (PMID 37342342, 2023). "However, MOG-IgG are also found in other CNS demyelinating syndromes such as unilateral or bilateral optic neuritis, myelitis or acute disseminated encephalomyelitis (ADEM)." (PMID 36451827, 2022). "The clinical symptoms of patients with MOG-AD can be present in other CNS demyelinating diseases, including acute disseminated encephalomyelitis (ADEM), optic neuritis (ON), neuromyelitis optica spectrum disorder (NMOSD), brainstem encephalitis, or multiple sclerosis (MS)." (PMID 35958613, 2022). "Using cutting-edge detection technologies, anti-MOG antibodies were found in a subset of pediatric patients with acute disseminated encephalomyelitis (ADEM), patients with clinical symptoms of NMOSD, and patients with bilateral optic neuritis in particular (cell-based approaches)." (PMID 35684455, 2022). "MOG-ab-positive children more frequently presented with acute disseminated encephalomyelitis, had deep gray matter lesions on MRI, had a better clinical and radiological recovery, and were less likely to have sustained disability than AQP4-ab-positive children." (PMID 33841310, 2021). "Clinical manifestations of MOG-antibody-associated disease (MOGAD) may include the typical NMO phenotype, be limited to isolated optic neuritis (in adults) or develop into acute disseminated encephalomyelitis (ADEM—mostly seen in children)." (PMID 33802046, 2021). "A recent study showed in the setting of an acute disseminated encephalomyelitis model with influenza infection, that uptake of the self-antigen myelin oligodendrocyte glycoprotein (MOG) via the BCR could occur concurrent with influenza hemagglutinin (HA)." (PMID 29887868, 2018).
acute disseminated encephalomyelitis (continued). "Monophasic acute disseminated encephalomyelitis and pediatric MS might also be separated by MOG antibodies because these antibodies tend to persist longer in pediatric MS." (PMID 23035757, 2012). "MOG antibodies are relevant not only in acute disseminated encephalomyelitis (ADEM) but also in a subset of children presenting with isolated cerebellar ataxia, some of whom experience a relapsing course, even with normal initial MRI findings." (PMID 41321459, 2025). "Beside MS, ADS in children under 18 years of age may also include anti-aquaporin-4-associated neuromyelitis optica spectrum disorder (AQP4-NMOSD), myelin oligodendrocyte glycoprotein antibody-associated disorder (MOGAD), or acute disseminated encephalomyelitis (ADEM) with encephalopathy." (PMID 39845956, 2024). "The first patient, a 44-year-old black African man, presented with acute disseminated encephalomyelitis (ADEM) with positive serum MOG antibodies." (PMID 37845760, 2023). "Besides MS and NMOSD, MOG-IgG is considered to be related to other idiopathic inflammatory demyelinating diseases (IIDDs), including acute disseminated encephalomyelitis (ADEM), optic neuritis (ON), transverse myelitis (TM), and clinically isolated syndrome (CIS)." (PMID 34093424, 2021). "Among patients with MOG-Ab disease, brain manifestations constituted an acute disseminated encephalomyelitis (ADEM)–like presentation that occurred in 4 patients (9%)." (PMID 31596489, 2019). "Another newly discovered biomarker is the anti-MOG antibody found in the CSF of patients with demyelinating diseases such as optic neuritis (usually recurrent), myelitis encephalitis, brainstem encephalitis, and acute disseminated encephalomyelitis (ADEM)-like presentations." (PMID 31031747, 2019). "In the past, MOG-Abs were particularly described in acute disseminated encephalomyelitis (ADEM), an inflammatory CNS disorder that, if it has an pediatric onset, is mostly monophasic and has a favorable outcome in the majority of cases." (PMID 30405519, 2018). "Other examples of B cell-related autoimmune demyelinating CNS conditions are pediatric MS and acute disseminated encephalomyelitis (ADEM), where antibodies to myelin oligodendrocyte glycoprotein (MOG) have been identified." (PMID 26648933, 2015). "Since anti-MOG antibodies are also found in pediatric MS and acute disseminated encephalomyelitis (ADEM) the picture emerges that the age of disease onset influences the nature of the autoantigen." (PMID 25889963, 2015). "More recently, with the use of different cell-based assays, anti-MOG antibodies could be identified in a subgroup of pediatric ADEM (acute disseminated encephalomyelitis), CIS (clinically isolated syndrome), or MS and were shown to correlate with the disease course." (PMID 26197319, 2015). "In a microarray assay assessing antibody reactivity against a broad spectrum of antigens to differentiate MS from acute disseminated encephalomyelitis (ADEM), the presence of anti-MOBP IgG was more indicative of ADEM than of MS, which parallels findings on MOG antibodies." (PMID 41226806, 2025). "Individuals testing positive for MOG-IgG may present with clinical manifestations such as optic neuritis, transverse myelitis, acute disseminated encephalomyelitis (ADEM), or encephalitis with the involvement of the cerebral cortex, cerebellum, or brainstem." (PMID 40362691, 2025). "Given the appearance of imaging findings and patient’s age, demyelinating conditions such as multiple sclerosis, neuromyelitis optica (NMO), myelin-oligodendrocyte glycoprotein antibody-associated disease (MOGAD), and acute disseminated encephalomyelitis (ADEM) should be considered." (PMID 39308457, 2024). "Furthermore, anti-NMDAR encephalitis has been reported in association with the central nervous system demyelinating diseases, such as ADEM (acute disseminated encephalomyelitis), MOG-antibody related disease and NMOSD." (PMID 35527314, 2022).
acute disseminated encephalomyelitis (continued). "Furthermore, multiple onsets like acute disseminated encephalomyelitis (ADEM) plus optic neuritis (ON) or ON plus transverse myelitis (TM), etc., represent high relapse frequency in a shorter time for the children with MOG antibody-positive NMOSDs." (PMID 35250969, 2022). "The MOG antibody has been identified in inflammatory demyelinating diseases (IDDs), including acute disseminated encephalomyelitis (ADEM), neuromyelitis optica spectrum disorders (NMOSDs), optic neuritis (ON), transverse myelitis (TM), clinically isolated syndrome, and multiple sclerosis (MS)." (PMID 33419414, 2021). "A percentage of acute disseminated encephalomyelitis (ADEM) and NMOSD AQP4-Ab-seronegative patients were seropositive to MOG-Ab34." (PMID 31695085, 2019). "However, MOG-IgG has also been reported in, mostly pediatric, patients with acute disseminated encephalomyelitis (ADEM)." (PMID 27788675, 2016). "An acute disseminated encephalomyelitis–like presentation occurred at the time of the TM in 4 patients (9%) with MOG-Ab disease but no patients with AQP4-Ab disease." (PMID 31596489, 2019). "We measured 34 cytokines/chemokines using multiplex immunoassay in CSF collected from paediatric patients with serum MOG Ab POS [acute disseminated encephalomyelitis (ADEM = 8), transverse myelitis (TM = 2) n = 10] and serum MOG Ab NEG (ADEM = 5, TM = 4, n = 9) demyelination." (PMID 26919719, 2016). "Additionally, a patient suspected of acute disseminated encephalomyelitis (PT-32) showed demyelination on brain biopsy but was negative for MOG, AQP4 and GFAP antibodies." (PMID 40342619, 2025). "The clinical and radiological phenotype of MOG-AD partly overlaps with NMOSD and acute disseminated encephalomyelitis (ADEM)." (PMID 36472724, 2024). "The presence of MOG-IgG also occurs in some patients that can be clinically diagnosed with aquaporin-4-IgG seronegative NMOSD, acute disseminated encephalomyelitis (ADEM), and cortical encephalitis." (PMID 34025652, 2021). "However, the clinical spectrum of MOG-Abs is broader and includes longitudinally extensive transverse myelitis (LETM), acute disseminated encephalomyelitis (ADEM), and brainstem syndrome, as described by the two longest studies and other studies." (PMID 31736862, 2019). "Anti-Myelin oligodendrocyte glycoprotein (MOG) antibodies are detected in various demyelinating diseases, such as pediatric acute disseminated encephalomyelitis (ADEM), recurrent optic neuritis, and aquaporin-4 antibody-seronegative neuromyelitis optica spectrum disorder." (PMID 28420330, 2017). "This study aimed to compare the clinical, radiological, therapeutic, and prognostic differences between pediatric patients showing acute disseminated encephalomyelitis (ADEM) with and without myelin oligodendrocyte glycoprotein (MOG) antibodies." (PMID 37274199, 2023). "More recently, antibodies against conformational epitopes of the myelin oligodendrocyte glycoprotein (MOG) have been reported in AQP4-Ab negative NMOSD as well as in pediatric acute disseminated encephalomyelitis (ADEM)." (PMID 29208041, 2017).